MIR5692C1 (microRNA 5692c-1)
Synonyms: hsa-mir-5692c-1
Gene: MicroRNA gene on chromosome 5 (135,802,985 to 135,803,075, reverse strand). Ensembl gene ENSG00000265924.
Homologues: Orthologues: chimpanzee MIR5692C1 (100% identical).